FGFR1 (fibroblast growth factor receptor 1)
Diseases named in the same sentence as FGFR1 in open-access papers (continued):
Sharing a sentence is not in itself a finding about the gene and the disease.
lung carcinoma (continued). "Specifically, in lung cancer cell lines with amplified FGFR1, MET overexpression induces resistance to FGFR inhibitors, indicating a possible inverse correlation between these pathways." (PMID 39544292, 2024). "FGFR1-amplification in lung cancer cell lines H1581 and DMS1144 was shown to promote EMT, migration, and invasion, which were attributed to SOX2 expression." (PMID 38612911, 2024). "FGF2-mediated activation of FGFR1 promotes resistance to EGFR inhibitors in lung cancer, FLT3 inhibitors in AML, and KIT inhibitors in gastrointestinal stromal tumors." (PMID 37598282, 2023). "In summary, we found 2 additional primary tumors with tail-to-tail rearrangements within FGFR1, suggesting that rearrangements within FGFR1 are recurrent events in 8p11-p12–amplified lung cancer." (PMID 37606995, 2023). "We focused our analysis on 8 FGFR1-amplified lung cancer cell lines treated with the small-molecule inhibitors BGJ398 and AZD4547." (PMID 37606995, 2023). "Tumors from patients with lung cancer who respond to FGFR inhibition exhibit tail-to-tail rearrangements within FGFR1." (PMID 37606995, 2023). "One of the most frequent alterations is FGFR1 gene amplification, notably occurring in ovarian cancer, head and neck cancer, urothelial cancer and lung cancer, with a frequency of 9 to 28%." (PMID 37445817, 2023). "FGF8 activates FGFR1 by directly binding to it, which aggravates lung cancer and results in the phosphorylation of ERK1/2." (PMID 36629518, 2023). "In conclusion, FGF18 plays an important role in promoting the growth and tissue progression of lung cancer cells through FGFR1-ERK/p38 pathway." (PMID 37228502, 2023). "Fibroblast growth factor receptor 1 (FGFR1) Fc fusion protein (FP-1039) inhibited the growth of five lung cancer cell lines NCI-H1581, NCI-H520, DMS114, NCI-H1703 and DMS53." (PMID 37228502, 2023). "However, to the best of our knowledge, the present study is the first to investigate the mechanism of FGFR1 resistance in a large-scale phosphoproteomic mass-spectrometry investigation, which included intrinsically resistant, induced-resistant and mutationally induced-resistant lung-cancer cells." (PMID 35853934, 2022). "Increased FGFR1 expression is frequent across various lung cancer histologies, namely, squamous cell carcinomas and adenocarcinomas." (PMID 35402275, 2022). "Activation of FGFR1 is linked to EMT in prostate cancer, and both EMT and upregulation of FGFR1 has been linked to resistance to targeted therapies in lung cancers." (PMID 35963908, 2022). "For this, we selected lung cancer cell lines with amplified or overexpressed FGFR1-3, or any of the FGF family that were overexpressed." (PMID 36139037, 2022). "Co-inhibition of AKT/FGFR1, CD44/FGFR1 or PAK1/FGFR1 sensitized ‘intrinsically resistant’ and ‘induced-resistant’ lung-cancer cells synergetically to FGFR1 inhibition." (PMID 35853934, 2022). "Among the GFRs, hypoxia increased the expression of fibroblast growth factor receptor 1 (FGFR1) via the MAPK signaling pathway in lung cancer cell lines and xenograft models." (PMID 35681691, 2022). "For example, FGFR1 amplification was found in approximately 6% of lung cancer cases, mainly in squamous non-small cell lung carcinoma subtype without effective treatments 1,4." (PMID 36168616, 2022). "Several previous studies reported the prognostic value of a single immune-related gene in EPC or lung cancer, such as FGFR1, TNFRSF10B, and IL1B." (PMID 36147506, 2022). "In conclusion, we used a phosphoproteomic approach to investigate diverse resistance mechanisms to FGFR1 inhibition in lung-cancer cells." (PMID 35853934, 2022). "In order to understand the complex signaling paths that lead to mechanisms of resistance to FGFR1 inhibition in lung cancer, we here performed for the first time a large-scale mass-spectrometric phosphoproteomic analysis of FGFR1-amplified lung cancer cells." (PMID 35853934, 2022).
lung carcinoma (continued). "We picked a few breast and lung cancer cell lines and validated the amplified status of 4EBP1 and FGFR1 proteins by Western blotting analysis." (PMID 35626002, 2022). "miR-214-3p is downregulated in lung cancer patients and acts as a vital target in FGFR1-amplified patients by forming a miR-214-3p-FGFR1-Wnt/MAPK/AKT signalling pathway network." (PMID 36121543, 2022). "Co-inhibition of CD44, Pak1 or AKT together with FGFR1 (re-)sensitized resistant lung cancer cells to FGFR1-targeted therapy." (PMID 35853934, 2022). "Synergism between MEK and FGFR inhibition has previously been established in the context of KRAS mutant lung cancer: a shRNA screen of Tra-treated H23 KRASG12C lung cancer cells identified FGFR1 signaling as compensatory for MEK inhibition." (PMID 35739276, 2022). "MiR-214-3p has also been shown to be downregulated in FGFR-amplified lung cancer and its overexpression was found to inhibit proliferation, migration, and invasion of lung cancer cells by targeting FGFR1." (PMID 36471277, 2022). "It has been reported that several oncogenic tyrosine kinases phosphorylated LDHA at Y10 in various cancers, such as FGFR1 in lung cancer, BCR-Abl in chronic myelogenous leukemia, and JAK2 in human erythroleukemia." (PMID 35525866, 2022). "8p11-12-amplified breast and lung cancer were highly sensitive to FGFR1 and PI3K inhibitors, and this effect was abolished in 4EBP1 CRISPR-cas9 knockout cells." (PMID 35626002, 2022). "In the present project, we aimed to investigate resistance mechanisms to FGFR1 inhibition in lung-cancer cells with FGFR1 gene amplification." (PMID 35853934, 2022). "We identified a CD44/PAK1/AKT signaling axis as a commonly occurring resistance mechanism to FGFR1 inhibition in lung cancer." (PMID 35853934, 2022). "Fibroblast growth factor receptors (FGFRs), consisting of FGFR1, FGFR2, FGFR3 and FGFR4, are implicated in the progression of a range of cancers; in particular, FGFR1 shows oncogenic traits in lung cancer." (PMID 36482474, 2022). "It was reported that several oncogenic tyrosine kinases phosphorylated LDHA at Y10 in various cancers, such as FGFR1 in lung cancer, BCR-Abl in chronic myelogenous leukemia, and JAK2 in human erythroleukemia." (PMID 35525866, 2022). "In this study, we explored the contribution of FGFR1/4EBP1 amplification in mediating translation activation and cancer progression in breast and lung cancer." (PMID 35626002, 2022). "PI3KCA signaling was downstream of FGFR1, and therefore PI3KCA-mutated cells showed reduced sensitivity to the FGFR1 inhibitor ponatinib when compared to wild-type PI3KCA cells in both breast and lung cancer cell lines, as observed in the database from DepMAP." (PMID 35626002, 2022). "For instance, miR-198 inhibits lung cancer cells and human osteosarcoma by directly targeting FGFR1 and ROCK1, respectively." (PMID 34289837, 2021). "Coactivation of HER2 and PDGFRα caused by gene amplification or ligand overexpression has also been shown to activate the PI3K-AKT signalling and to reduce FGFR TKI-mediated MAPK signalling inhibition in an FGFR1-amplified lung cancer cell line." (PMID 34068816, 2021). "Gene fusions with FGFR1 have been found in myeloid/lymphoid neoplasm, lung cancer, papillary thyroid carcinoma, low‐grade gliomas and phosphaturic mesenchymal tumour." (PMID 33655556, 2021). "This ligand trap has been shown to be able to block FGF2-dependent cell proliferation and inhibit the growth of several cancers in xenograft models, including FGFR1-amplified lung cancer and FGF2-overexpressing mesothelioma." (PMID 34830951, 2021).
lung carcinoma (continued). "Preclinical data showed that erdafitinib has the potential to induce a prolonged inhibition of FGFR signalling, which is accompanied by reduced proliferation in a range of human lung cancer cell lines with FGFR1 amplifications." (PMID 34068816, 2021). "Inhibition of FGFR3 in a urothelial cancer cell line or FGFR1 in a lung cancer cell line resulted in decreased c-MYC protein level." (PMID 34830951, 2021). "FGFR1 is frequently amplified in lung cancer and is a latent curative target in many solid tumor as well." (PMID 33928031, 2021). "Here, we suggest that FGFR1 overexpression contributes to resistance to KRASG12C inhibitors in lung cancer." (PMID 34858498, 2021). "To check if in vitro FGFR1 binding translates to efficient binding and internalization into FGFR1-expressing cells, we used lung cancer cell lines characterized with regard to FGFR1 expression levels." (PMID 34867353, 2021). "Previous studies confirmed that FGF2 exerts its biological function via combining FGF receptor 1(FGFR1) in lung cancer cells." (PMID 34873170, 2021). "Further corroborating the antagonistic role of autophagy, the clinically approved autophagy inhibitor chloroquine potently enhances the cytotoxicity of FGFR1/PLK1 inhibitors in KRAS‐mutant lung cancer cells in vitro and in vivo." (PMID 34369083, 2021). "FGFR1/4 overexpression in lung cancer has been suggested as a biomarker for poor outcomes and FGFR-targeting therapy when co-expressed with N-cadherin." (PMID 34068954, 2021). "In previous studies, our group has demonstrated that FGFR1 interacted with Gli2, SOX2 and YAP to maintain stemness or EMT in FGFR1 amplified lung cancer, especially in LSCC." (PMID 32380883, 2020). "In lung SCC, some researchers suggested the mechanism of discrepancy between protein expression and gene amplification of FGFR1 due to crosstalk between FGFR1 and co-activated RTKs in FGFR1-amplified lung cancers with low FGFR1 protein expression." (PMID 32326908, 2020). "In our study, we investigate correlation between FGFR1 gene amplification, protein expression, clinicopathological characteristics, and prognosis of lung cancer patients." (PMID 32207251, 2020). "Si-CCND1 proved significant antitumor effect in the genetic background of FGFR1 amplified lung cancer." (PMID 32380883, 2020). "The level of FGFR1 is found in many human cancers, including prostate cancer, lung cancer, and gastric cancer." (PMID 32202509, 2020). "Of the two main types of lung cancer, small cell lung cancer (SCLC) and non-small cell lung cancer (NSCLC), which accounts for 85% of lung carcinomas, FGFR1 is amplified in 22% of squamous cell lung carcinomas, a subtype of NSCLC." (PMID 32369771, 2020). "EGFR and FGFR1 appear to work together to increase tumorgenicity in lung cancer, and active FGFR1 can increase resistance to EGFR targeted therapies." (PMID 32209086, 2020). "The FGFR1–ERK1/2–SOX2 axis promotes cell proliferation, epithelial–mesenchymal transition (EMT), and metastasis in FGFR1-amplified lung cancer." (PMID 32244796, 2020). "Cytotoxic potency was evaluated on FGFR1-positive cell lines—model engineered cell line (U2OS-FGFR1) and lung cancer cell line (NCI-H520)." (PMID 33076489, 2020). "Here, we analyzed prevalence and correlation of FGFR1 gene amplification and protein expression in human lung cancer and their impact on overall survival." (PMID 32207251, 2020). "A total number of 421 lung cancer patient samples were collected to study gene amplification and protein expression of FGFR1 in human lung cancer." (PMID 32207251, 2020). "Our work has evaluated prevalence and correlation of FGFR1 gene amplification and protein expression in 421 lung cancer patient samples." (PMID 32207251, 2020). "To further explore the functional pattern of miR-214-3p in FGFR1-amplified lung cancer, we performed GO data analysis to search the cross-signaling, and the Wnt signaling was found to be an intersection." (PMID 31492847, 2019).
lung carcinoma (continued). "STAT3 has also been implicated in mediating resistance to AZD4547 and infigratinib in H1581 lung cancer cells (FGFR1 amplified) following induction of cognate receptors by the secretome." (PMID 35582593, 2019). "miR-214-3p acts as a vital target in FGFR1-amplified lung cancer by forming a miR-214-3p-FGFR1-Wnt/MAPK/AKT signaling pathway network." (PMID 31492847, 2019). "We confirmed that FGFR1 was a direct target of miR-214-3p and mediated the biological function of miR-214-3p in FGFR1-amplified lung cancer cells." (PMID 31492847, 2019). "Increased PI3K/AKT/mTOR signaling, independent of changes in upstream receptor tyrosine kinases has been described in DMS114 lung cancer cells (FGFR1 amplified) and RT112 urothelial cancer cells (FGFR3-TACC3) following chronic treatment with infigratinib." (PMID 35582593, 2019). "The FGFR inhibitor UPR1376, a chloroacetamide derivative has demonstrated preclinical anti-tumour activity in FGFR1 amplified lung cancer cell lines with acquired resistance to infigratinib." (PMID 35582593, 2019). "GSK3052230, a novel engineered FGF trap comprised of the extracellular domain of FGFR1 fused to the Fc portion and is in clinical testing in lung carcinoma (NCT01868022)." (PMID 35582593, 2019). "Sox2, an essential transcriptional factor of CSCs, was upregulated after FGFR1 activation, and FGFR1 signaling has been shown to contribute to the maintenance of CSC properties by interacting with the Hippo/YAP1 pathway in lung cancer." (PMID 31801598, 2019). "On the other hand, FGFR1 is relatively frequently amplified and over-expressed in breast and lung cancer and is currently widely accepted to have a carcinogenic effect." (PMID 31754359, 2019). "FGFR1-amplified lung cancer cell lines have shown promising preclinical sensitivity to kinase inhibition." (PMID 31492847, 2019). "In conclusion, our study demonstrated the regulatory mechanism between miR-214-3p and FGFR1 in lung cancer." (PMID 31492847, 2019). "To date, studies have unveiled a large amount of miRNA signatures in lung cancer, yet miRNA dysregulation in FGFR1-amplified lung cancer has remained unclear." (PMID 31492847, 2019). "Upregulation of the receptor tyrosine kinase MET has been described in DMS114 lung cancer cells (FGFR1 amplified), made resistant to infigratinib and H1581 lung cancer cells (FGFR1 amplified) made resistant to AZD4547 and the FGFR inhibitor rogaratinib." (PMID 35582593, 2019). "In lung cancer, FGFR1 amplification is observed in 9–20% of cases of the Squamous Non-Small-Cell Lung Cancer (SQCLC) histotype." (PMID 30972293, 2019). "Aberrant FGFR1 expression contributes to metastasis in prostate and lung cancers and hepatocellular carcinoma." (PMID 30326563, 2018). "Activating mutations in FGFR1 were found in glioblastoma, FGFR2 is often mutated in endometrial carcinomas and lung cancers, FGFR3 mutations are frequently found in bladder tumors and melanoma, whereas FGFR4 is mutated in endometrial and lung cancers." (PMID 30577533, 2018). "It has been reported that cellular apoptosis was obviously observed after FGFR1-amplified lung cancer cell lines were treated with the specific inhibitor (PD173074)." (PMID 30567360, 2018). "The results of in vitro and in vivo clinical studies clearly indicated that not all FGFR1-amplified LSQCCs are sensitive to FGFR inhibitors and this observation suggests that some mechanisms of primary resistance are frequent in FGFR1-amplified lung cancer." (PMID 30060526, 2018). "The FGF-based conjugates retained the receptor binding and cellular trafficking properties of unconjugated FGFs, and demonstrated a selective cytotoxic potential against FGFR1-overproducing lung cancer cell lines." (PMID 30577533, 2018). "The screens identified MTOR as a high-ranking synthetic lethal hit in the setting of FGFR-specific TKIs in FGFR1-driven lung cancer and HNSCC cell lines." (PMID 29458371, 2018).
lung carcinoma (continued). "Here, we show that miR-16 levels in lung fibroblasts control HGF production in an FGFR1-dependent manner unraveling a novel mechanism of communication between stromal and neoplastic cells in lung cancer, with potential clinical implications." (PMID 29558956, 2018). "To gain a deeper insight into this matter in lung cancer, we used the FGFR1-amplified DMS114 cell line and generated multiple clones with AR to an FGFR1-TKI." (PMID 30140389, 2018). "Mutations in FGFR2 and FGFR3 have also been reported in other tumor forms, whereas activation of FGFR1 has mainly been observed in the form of FGFR1 amplification in breast and lung cancer." (PMID 29159601, 2018). "This feature enabled detection of this agent at subcellular level in FGFR1-amplified lung cancer cells in live and fixed cell conditions and revealed lysosomal sequestration to limit its cytotoxic potential." (PMID 30544798, 2018). "In head and neck squamous cell cancers and various lung cancers, FGFR1 expression has, in fact, been shown to predict treatment responses better than genomic alterations in FGFR1." (PMID 28468611, 2017). "Based on this unique characteristic, nintedanib transport by ABCB1 was exemplarily dissected and inactivation by lysosomal trapping was identified to represent a novel resistance mechanism limiting nintedanib activity in FGFR1 amplification-driven lung cancer." (PMID 28882160, 2017). "In preclinical explant models of lung cancer, FGFR1 amplification conferred sensitivity to AZD4547 treatment." (PMID 26905262, 2016). "Together, these results showed that GLI2 was involved in FGFR1-dependent Hedgehog signaling pathway, which was critical for maintaining the stem-like phenotype of FGFR1 -amplified lung cancer cells." (PMID 26936993, 2016). "Taken together, these data demonstrate that FGFR1 amplification predicts for sensitivity to AZD4547 treatment within the cohort of lung cancer cell lines." (PMID 26905262, 2016). "Together our study suggests that the FGFR1/GLI2 axis promotes the lung cancer stem cell-like phenotype." (PMID 26936993, 2016). "In conclusion, our data provide strong evidence that FGFR1 signaling plays an important role in regulating brachyury-driven lung cancer cellular processes by MAPK." (PMID 27893433, 2016). "All these lung cancer cell lines bear amplification of the FGFR1 gene (shown for DMS114) and have previously been shown to be hypersensitive to FGFR tyrosine kinase inhibition." (PMID 27367030, 2016). "Here we found that fibroblast growth factor receptor 1/mitogen-activated protein kinase (FGFR1/MAPK) signaling regulated brachyury in lung cancer." (PMID 27893433, 2016). "We further assessed the relationship between sensitivity to FGFR inhibition and FGFR1 copy number in a panel of lung cancer cell lines, comprising of 15 sqNSCLC cell lines and the small cell lung cancer cell line DMS114." (PMID 26905262, 2016). "High expression of FGFR1 protein indicates a poor prognosis for multiple tumor types, including lung cancer, triple-negative breast cancer, and gastric cancer." (PMID 26993773, 2016). "Genomically amplified fibroblast growth factor receptor 1 (FGFR1) is an oncogenic driver in defined lung cancer subgroups and predicts sensibility against FGFR1 inhibitors in this patient cohort." (PMID 27367030, 2016). "Herein for the first time we demonstrated that FGFR1 promoted stem cell-like phenotype in lung cancer cells harboring FGFR1 amplification, especially in LSCC, partly through stimulating the expression and activity of GLI2." (PMID 26936993, 2016). "Herein, for the first time we demonstrated that FGFR1 maintained a highly tumorigenic phenotype in lung cancer cells harboring FGFR1 amplification, and in LSCC tumors." (PMID 26936993, 2016). "In vitro, fibroblast growth factor receptor 1 (FGFR1) activation was reported as an escape mechanism in human lung cancer cells resistant to afatinib." (PMID 26862733, 2016).